C10orf67 (chromosome 10 open reading frame 67)
Synonyms: LINC01552; MGC46732; bA215C7.4; C10orf115
Tractability: No criterion of Open Targets' tractability assessment is met for any kind of drug.
Gene: Protein-coding gene on chromosome 10 (23,202,696 to 23,344,845, reverse strand). Ensembl gene ENSG00000179133.
Subcellular location: Mitochondrion
Subcellular location (Human Protein Atlas): Microtubules; Mitochondria; Vesicles
Gene Ontology:
Molecular function: protein binding
Cellular component: mitochondrion
Genetic constraint (gnomAD): Loss-of-function variants: 21 observed, 14.74 expected, observed/expected ratio (o/e) 1.42, 90% interval 1 to 1.89. The upper end of that interval is the gene's LOEUF score, 1.89, which puts it in group 6 of 6, group 1 being the genes least tolerant of losing a copy. Missense variants: 190 observed, 156.97 expected, observed/expected ratio (o/e) 1.21, 90% interval 1.08 to 1.37. Synonymous variants: 69 observed, 56.52 expected, observed/expected ratio (o/e) 1.22, 90% interval 1 to 1.49.
Homologues: Orthologues: chimpanzee C10H10orf67 (99% identical), macaque C9H10orf67 (78% identical), dog C10orf67 (57% identical), mouse 4921504E06Rik (45% identical), rat C17h10orf67 (44% identical), zebrafish si:dkey-188g12.1 (22% identical), tropical clawed frog c6h10orf67 (21% identical).
Diseases named in the same sentence as C10orf67 in open-access papers:
C10orf67 is named in the same sentence as 4 diseases in open-access papers, as found by Europe PMC text mining. Sharing a sentence is not in itself a finding about the gene and the disease. The quoted sentences say what the papers report.
sarcoidosis (3 papers, 2012 to 2016). Sarcoidosis is a multisystemic disorder of unknown cause characterized by the formation of immune granulomas in involved organs. "C10orf67 was found following a genome scan to isolate genes associated with sarcoidosis and CD." (PMID 27812135, 2016). "It is worth noting that we did not replicate the association with C10orf67 as identified in a joint GWAS of German patients with either sarcoidosis or Crohn’s disease." (PMID 22952805, 2012).
C10orf67 also shares sentences with these, for which no sentence is quoted: Crohn disease (2 papers); cancer (1); tumour (1).